ART5 (ADP-ribosyltransferase 5)
Synonyms: ARTC5
Tractability: Antibody: UniProt places it where antibodies can reach, with high confidence; UniProt predicts a signal peptide or a membrane-spanning region; its Gene Ontology location is reachable by antibodies, with medium confidence.
Gene: Protein-coding gene on chromosome 11 (3,638,503 to 3,643,187, reverse strand). Ensembl gene ENSG00000167311.
Subcellular location: Secreted
Gene Ontology:
Molecular function: protein binding; NAD+ poly-ADP-ribosyltransferase activity; NAD+-protein-arginine ADP-ribosyltransferase activity
Cellular component: extracellular region
Genetic constraint (gnomAD): Loss-of-function variants: 23 observed, 24.46 expected, observed/expected ratio (o/e) 0.94, 90% interval 0.68 to 1.33. The upper end of that interval is the gene's LOEUF score, 1.33, which puts it in group 5 of 6, group 1 being the genes least tolerant of losing a copy. Missense variants: 402 observed, 377.66 expected, observed/expected ratio (o/e) 1.06, 90% interval 0.98 to 1.16. Synonymous variants: 161 observed, 157.36 expected, observed/expected ratio (o/e) 1.02, 90% interval 0.9 to 1.17.
Homologues: Orthologues: chimpanzee ART5 (99% identical), macaque ART5 (90% identical), rabbit ART5 (85% identical), dog ART5 (83% identical), guinea pig ART5 (80% identical), mouse Art5 (79% identical), rat Art5 (79% identical), pig ART5 (69% identical), zebrafish si:ch211-145b13.6 (16% identical). Paralogues in human: ART3 (36% identical), ART1 (35% identical), ART4 (29% identical).
Diseases named in the same sentence as ART5 in open-access papers:
ART5 is named in the same sentence as 5 diseases in open-access papers, as found by Europe PMC text mining. Sharing a sentence is not in itself a finding about the gene and the disease. The quoted sentences say what the papers report.
ARTEMIS deficiency (1 paper, 2022). "In addition to DDR, we investigated the expression of T cell receptor alpha V7.2 (TCRaV7.2) on CD45+CD3+ T cells of all patients analyzed, including an additional patient with ARTEMIS deficiency and maternal–fetal T cell transfusion (ART5), and 21 healthy controls." (PMID 34716846, 2022).
ART5 also shares sentences with these, for which no sentence is quoted: Arthritis (1 paper); colorectal cancer (1); malaria (1); rheumatoid arthritis (1).